IL18 (interleukin 18)
Diseases named in the same sentence as IL18 in open-access papers (continued):
Sharing a sentence is not in itself a finding about the gene and the disease.
tumor (continued). "The presence of a tumor-specific eQTL for Il18 may reflect differences in the relative proportions of epithelial and inflammatory cells in the tumors, or may be due to rewiring of Il18 signaling during progression." (PMID 21244661, 2011). "However, at the moment RVL has not yet been reported as a potential inhibitor of prometastatic effects of hepatic inflammation created in the liver microenvironment by tumor-induced IL-18." (PMID 21569399, 2011). "Moreover, IL-18 therapy restricted ascites accumulation, a reliable surrogate of i.p. tumor growth (p < 0.05), and prolonged the survival of ID8-Vegf tumor-bearing mice (p < 0.05)." (PMID 21609494, 2011). "The median tumor weight in the control group was 714 mg (interquartile range 470-1278); in the topotecan group it was 419 mg (325-540, p = 0.06); in the IL-18 group it was 437.5 mg (240-650, p = 0.066); and in the combination group it was 267 mg (160-360, p = 0.012)." (PMID 21609494, 2011). "We hypothesized that tumor surviving Doxil chemotherapy becomes sensitized to cytotoxic lymphocytes and can be effectively targeted by the immune response activated by IL-18, providing the basis for positive therapeutic interactions." (PMID 20003308, 2009). "Additionally, IL-18 augments the efficacy of DC-based vaccines as well as whole-cell tumor vaccines." (PMID 18818761, 2008). "Furthermore, IL-18-transfected tumor cell vaccines and local delivery of the IL-18 gene as naked DNA via a gene gun or viral vectors has been extensively investigated." (PMID 17519043, 2007). "The results suggest that mIL-18 DNA is expressed in the tumor site, and releases bioactive IL-18." (PMID 17519043, 2007). "However, IL-18 is also recognized as a tumor-promoting factor." (PMID 41522514, 2026). "However, a comparative study assessing NLRP3 (NOD-like receptor protein 3), caspase-1, IL-1β, and IL-18 mRNA and protein expression in hen and human OvCa found increased protein expression of caspase-1, IL-1β, and IL-18 in surface epithelium, tumor cells, and immune cells." (PMID 40718836, 2025). "In addition, relevant studies on CAR T cells secreting IL-18 showed that these cells had increased proliferation and infiltration ability and could recruit endogenous immune cells to regulate the tumor microenvironment." (PMID 40244018, 2025). "Therefore, we hypothesized that tumor-derived IL-33 and IL-18 might influence ILC2 frequency and function in PCa." (PMID 40247153, 2025). "Additionally, release of LDH, IL-18, and IL-1β were detected in both serum and tumor samples." (PMID 41415273, 2025). "Therefore, this study investigated the protein expression of NLRP3, ASC, caspase‐1, IL‐1B, IL‐18, IL‐1RA, and IL‐18BP on tumor cells by utilizing multiplexed immunohistochemistry on PDAC and IPMN samples, examining their association with pathological features and prognoses." (PMID 39969214, 2025). "However, a promising approach yet to be proven clinically is based on engineering CAR-T cells to produce IL-12 and IL-18 and converting the environment to an acute inflammatory state, enhancing T-cell activation and tumour control, especially in macrophage-rich tumours like SCLC." (PMID 40906384, 2025). "Thus, NAFT1 signaling could promote IL‐18 production through the p38 MAPK pathway in the spinal microglia after tumor inoculation." (PMID 39957627, 2025). "Contrary to previous research suggesting that the presence of tumor cells or tumor-related stimuli could stimulate IL-18 production, our findings suggest that high concentrations play an antitumor role, and their absence predisposes patients to develop disease." (PMID 40711287, 2025). "Moreover, IL-18 can also enhance the cytotoxic effector function of tumor-reactive Vδ2 T cells." (PMID 41306552, 2025). "Research suggests that a complete absence of IL‐18 (or its receptor IL‐18R) makes mice more susceptible to intestinal epithelial harm, and creates a modified inflammatory milieu that enhances the potential for intestinal tumor development." (PMID 40453734, 2025).
tumor (continued). "Furthermore, recombinant IL-18 has been used in clinical trials as an immunotherapy to enhance the activation of NK cells and T cells, which are critical for the recognition and elimination of tumor cells." (PMID 40141358, 2025). "Blocking NFAT1 or p38 MAPK could markedly suppress the expression of IL‐18 after tumor injection." (PMID 39957627, 2025). "Additionally, in human umbilical vein endothelial cells (HUVECs), 8 suppressed proliferation and angiogenesis, further supporting its anti-tumor-vascularization effects Under hypoxic conditions, 8 reduced interleukin-18 (IL-18) levels in a BXPC-3 cell culture medium." (PMID 40422787, 2025). "By combining cytokines (IL-12+IL-15+IL-18) to induce a memory-like phenotype, CAR-NK cells can acquire CD45RA-associated memory characteristics, with in vivo persistence extended beyond 60 days, and exhibit accelerated response kinetics upon secondary tumor challenge." (PMID 41488873, 2025). "We documented up-regulation in the expression of IFN-γ, IL12p70, IL-18, IL-20, MIF, TNF-α, TSLP, BLC, Eotaxin-1, Eotaxin-2, IP-10, MIP-1a, MIP-3a, FGF-2, MMP-1, TNFRII and TWEAK, which are implicated in the modulation of inflammation, apoptosis, tumor growth, invasion, and angiogenesis." (PMID 38954024, 2024). "Similarly, IL-18 has been reported to have potent anti-tumor effects." (PMID 39451257, 2024). "Therefore, even though constitutive high expression of IL-18 can lead to greater anti-tumor activity compared with inducible systems, the ability to control IL-18 secretion should still be considered a safer alternative for enhancing the anti-tumor activity of CAR-T cells." (PMID 39640015, 2024). "However, the influence of IL-1β and IL-18 on tumorigenesis is still debatable and may vary depending on the tumor context." (PMID 38523155, 2024). "Also, higher levels of IL-18 in serum and tumor are detected with IMSA101 treatment." (PMID 38730243, 2024). "Moreover, Interleukin 18 (IL-18), a pro-inflammatory cytokine, is up-regulated on tumor-infiltrating lymphocytes, suggesting that IL-18 therapy could enhance anti-tumor immunity." (PMID 38169571, 2024). "IL-1ꞵ is largely thought to promote tumor growth, and the vast majority of IL-1β-based therapies aim to block the cytokine and its signaling, while IL-18 is largely thought to promote antitumor immune responses, and many therapeutic efforts aim to boost IL-18 signaling." (PMID 38391959, 2024). "Besides IL-1β, myeloid cell-derived IL-18 also facilitates anti-tumor immunity." (PMID 36932407, 2023). "Moreover, mutant IL18 engineered for resistance to inhibitory binding of the high-affinity IL-18 decoy receptor also promoted the activity of NK cells, resulting in the enhancement of anti-tumor effects in mouse tumor models." (PMID 38139000, 2023). "Expression of Nnt is increased in Il18−/− mice, indicating that tumor growth might be promoted." (PMID 38139000, 2023). "Thus, IL-18 plays diverse roles in the regulation of tumor progression." (PMID 38066523, 2023). "In Il18−/− mice, Chrm1 expression was increased, indicating that tumor growth might be increased." (PMID 38139000, 2023). "Moreover, the presence of IL-1β and IL-18 can provide conducive conditions for tumor progression." (PMID 36882663, 2023). "IHC staining of two representative tumor specimens revealed that a high expression level of TMPRSS2 was accompanied by a high expression level of nuclear AhR and IL18, while a low expression level of TMPRSS2 was associated with a low expression level of nuclear AhR and IL18." (PMID 36975376, 2023). "Furthermore, if used together with lytic reactivation strategies, BILF1 antagonists could trigger tumor cell death, although also inducing pro-inflammatory IL-1 and IL-18 responses to induce cellular anti-tumor immune responses." (PMID 37311461, 2023).
tumor (continued). "P2RX7 can be considered to be a fine tuner of the tumor microenvironment, given that it is able to induce cell proliferation and death as well as to modulate the immune response through various pathways, notably through the release of IL-18 following the activation of the NLRP3 inflammasome." (PMID 37298187, 2023). "Furthermore, overexpression of the inflammatory cytokine IL-18, secreted by macrophages play a crucial role in the inflammatory and immune response and could mediate tumor suppression through the activation of natural killer (NK) and T cells." (PMID 35562533, 2022). "To validate expression of IL-12 and test whether tracer administration impacts downstream IL-12/IL-12R signaling, we performed qRT-PCR on flash frozen tumor tissue to measure expression of IL-12β and key proinflammatory cytokines indicative of active IL-12 signaling: IFNγ, TNFα, and IL-18." (PMID 35634303, 2022). "IL-18 might also play a role in tumor control and cancer chemotherapy/immunotherapy." (PMID 36032110, 2022). "Therefore, IL-18 may be considered to be a new tumor therapeutic target, and overcoming its avoidant immunophenotype may be a new cancer therapeutic strategy." (PMID 36675746, 2022). "There is no concrete evidence of the role IL-18 plays in bone metastasis up to now, while considering its association with angiogenesis, tumor cell migration, and metastasis, the following studies should focus on the function this cytokine has in bone metastasis." (PMID 36237303, 2022). "Notably, both IL-1β and IL-18 exert dual effects in tumor progression." (PMID 35739593, 2022). "Moreover, for cases having an increased NLR, the cytokines derived from neutrophils [like vascular endothelial growth factor, matrix metalloproteinases, and interleukin-18] may contribute to tumor growth." (PMID 35747263, 2022). "Also, mounting evidence suggests that IL18 is regulated by local microbial composition and changes induced by antibiotic treatment or other treatments (like chemotherapy) and therefore can be regarded as an influential dynamic factor in tumor biology." (PMID 36131941, 2022). "Furthermore, several studies indicated that IL‐18 enhances immunosuppressive response by promoting differentiation into monocytic myeloid‐derived suppressor cells (MDSCs), by inducing MDSCs migration into the tumor tissue." (PMID 33378581, 2021). "Moreover, IL-18-primed NK cells can cooperate with DCs to recruit effector T cells to tumor sites." (PMID 34177887, 2021). "Thus, IL‐18 may have a differential impact on tumor progression, which partly depends on the makeup of cytokine types." (PMID 34459122, 2021). "In addition, in this case, expression may be influenced by cytokine milieu in the tumor microenvironment, which selects, through the epigenetic role of some cytokines (TGF-β, IL-15 and IL-18), the NKp30 inhibitory variant and affects NK cell cytotoxicity." (PMID 33802077, 2021). "IL-18, originally termed IFNγ-inducing factor, is considered as a Th1-promoting cytokine since it elicits IFNγ production by T cells, which favors the generation and maintenance of a beneficial inflammatory microenvironment around tumor cells, with potential anti-tumor properties." (PMID 33430344, 2021). "Thus, IL-18 was found to be highly expressed in tumor cells in 72% of CRCs." (PMID 33430344, 2021). "Similarly, inflammasome-derived IL-18 also demonstrated dual effects in tumour progression." (PMID 33918087, 2021). "Therefore, due to its dual roles in both drug resistance and tumor metastasis, IL-18 may serve as a target for BC therapy." (PMID 33507690, 2021). "In addition, a significant association was observed between IL-18 levels and the percentages of aCasp1+ tumor cells, irrespective of the microsatellite status of CRC." (PMID 33430344, 2021).
tumor (continued). "Finally, the existence of a “paradoxical” subgroup of CRC (34% of CRCs) was identified that does not display an IFNγ response despite the secretion of mature IL-18 by tumor cells and that features downregulated IL-17, chemokines, and antimicrobial agent gene signatures." (PMID 33430344, 2021). "Moreover, since expression of IL‐12, IL‐15 and IL‐18 is upregulated, this may lead to formation of NK memory cells in the tumor microenvironment which needs to be further explored." (PMID 32821382, 2020). "Furthermore, CCL2, IL17, and IL18, which are increased in peripheral blood and tumor tissues, may recruit MDSC into tumor tissues." (PMID 32707869, 2020). "However, blocking inflammasomes may have limitations such as off-target effects, by inhibiting maturation of IL-18, an anti-tumor cytokine." (PMID 32635472, 2020). "Interestingly, LS MS3 induced 2.5-fold higher production of IL-18 in M2-like cells compared to M1-like cells, which may be indicative of a subset plasticity switch towards a pro-inflammatory/anti-tumour M1 phenotype." (PMID 32168834, 2020). "Moreover, studies illustrate the contribution of IL-18 during tumor metastasis development." (PMID 33015196, 2020). "First, IL-18 may exert its tumor-suppressive influences by stimulating IFN-γ production, promoting Th1 differentiation, enhancing the cytotoxic capacities of CD8+ lymphocytes and natural killer cells, inducing cancer cells to undergo programmed cell death, and suppressing the angiogenesis." (PMID 30925760, 2019). "Our data suggest that TGF-β1 and IL-18 may also profoundly modify the migratory capability of NK cells, limiting their extravasation and their encounter with other cell types present in inflamed tissues including tumor cells." (PMID 30641867, 2019). "The combined action of TGF-β1 and IL-18 on NKp30 expression may significantly impair the NK-mediated tumor immune surveillance as well as the “DC editing” process, allowing the survival of MHC class Ilow DCs that, due to the inappropriate antigen presentation, could promote tolerogenic responses." (PMID 30641867, 2019). "For instance, low doses of IL-18 were shown to accelerate tumor progression, in part through the induction of Kit+ immunosuppressive NK cells, while daily administration of IL-18 induced inflammation and increased the anti-tumor response, thus suppressing tumor growth." (PMID 31231372, 2019). "Soluble IL-18 is produced by stimulated antigen presenting cells, in particular by macrophages that, as M2-polarized cells, might represent the most abundant immune population in the tumor microenvironment." (PMID 30364222, 2018). "Besides the inhibition of tumor growth and induction of tumor tissue necrosis, we also observed the promotion of immune organ indices, monocyte/macrophage phagocytosis, splenic NK cell cytotoxicity, levels of IL-18 and hemolysin." (PMID 30002398, 2018). "Moreover, IL-18 secretion by tumor cells upregulates PD-1 expression on NK cells and PD-L1 expression on DC and may reduce numbers and actions of mature NK cells." (PMID 28286532, 2017). "Based on the increased expression of cytokines specific for activated DC (IL-12, IL-15 and IL-18) we have shown partial stimulation of specific cell types involved in cell-mediated immunity, although the only significant effect of immunization on the tumor size has been confirmed in IL-12." (PMID 28381295, 2017). "Furthermore, tumor derived IL-18 may offer a promising target for adjunct immune therapy for cancer." (PMID 28415798, 2017). "Thus, expanding Vγ2Vδ2 T cells with pulse zoledronate stimulation and either IL-18/IL-2, IL-21/IL-15, or IL-21/IL-2 could increase their anti-tumor immunity." (PMID 28239463, 2017). "Furthermore, several studies have shown the antitumor efficacy of IL-18 in animal tumor models." (PMID 26811064, 2016).
tumor (continued). "However, IL-18 represents a double-edged sword in cancer, since its activation may stimulate tumor development or oppositely, increase anti-tumor immunity and limit tumor growth through the activation of natural killer cell responses." (PMID 26437418, 2015). "In our study, the anti-tumor mechanism of membrane-bound GM-CSF and IL-18 might be similar." (PMID 26186692, 2015). "Furthermore, IL-18 can exert an antitumor effect by enhancing the activity of natural killer (NK) cells, reducing tumorigenesis, inducing tumor cell apoptosis and inhibiting tumor angiogenesis." (PMID 25780408, 2015). "Hence, the roles of IL-18 in cancer and cancer models are complex and may vary depending on the types of tumors and the companion therapy used to treat the tumor." (PMID 26378020, 2015). "It has been shown that IL-18 secreted by tumor cells could elicits an expansion of NK cells overexpressing PD-L1 with immunoablative functions by reducing the number of mature NK cells and dendritic cells (DC) in a PD-L1-mediated manner, at least in the B16F10 melanoma model in mice." (PMID 26779186, 2015). "In contrast, rejection is associated with massive infiltration of the tumor bed by leukocytes, predominantly ED1+ microglia/macrophages, CD4+ T helper cells and CD8+ effector cells, and correlates with elevated serum levels of pro-inflammatory cytokines IL-1β, IL-18 and TNF-α." (PMID 26291724, 2015). "However, we cannot exclude the possibility that IL-18 might also drive the anti-tumour immune response in vivo, particularly through enhanced production of IFN-γ during the early stages of T-ALL development." (PMID 24778454, 2014). "Furthermore, they found that its levels were correlation with IL-18 level, suggesting that these cytokines may act synergistically in the anti-tumor activity." (PMID 25005608, 2014). "The IL-18 cytokine, cleaved into its biologically active form by activated caspase-1, has emerged as a key cytokine downstream of inflammasome activation that enables epithelial repair after damage, but also prevents cancer progression through its induction of the tumor suppressors STAT1 and IFN-γ." (PMID 24795727, 2014). "The TK/GCV system results in tumor mass reduction, and local secretion of IL-18 may maintain the Th1 immunity and tumor-specific cytotoxic T lymphocytes (CTLs) induced by the APCs that process tumor antigens from the apoptotic tumor cells killed by the TK/GCV system." (PMID 25051201, 2014). "However, IL-18 has also been found to promote tumor progression." (PMID 24066061, 2013). "Therefore there might be a very different effect of inflammasome activity outside of the gut, wherein secreted IL-1β and IL-18 actually suppress tumor surveillance by innate cells but perhaps ultimately promote adaptive immunity to tumor antigens." (PMID 24409181, 2013). "It was reported that tumor-derived exosomes could induce specific antitumor responses when the parental tumor cells were genetically modified to express pro-inflammatory cytokines such as IL-18, IL-12, and IL-2 or when the parental tumor cells were subjected to stress conditions." (PMID 22190973, 2011). "First, we tested whether IL-18 exerts a direct cytotoxic effect on ID8 or ID8-Vegf tumor cells." (PMID 21609494, 2011). "However, increased levels of serum IL-18 has been reported to correlate with advanced disease, which mechanistically may reflect production by tumor-stimulated immune cells or by tumor cells themselves." (PMID 20003308, 2009). "Finally, IL-18 may have potential to augment the anti-tumor effects of donor leukocyte infusions by promoting effector T cells at the expense of regulatory T cell expansion." (PMID 18818761, 2008). "However, IL-18 has also been reported to enhance tumor progression." (PMID 18818761, 2008).